LINC01347 (long independently transcribed non-coding RNA 1347)
Gene: Transcribed unprocessed pseudogene on chromosome 1 (243,087,710 to 243,097,299, reverse strand). Ensembl gene ENSG00000214837.
Diseases named in the same sentence as LINC01347 in open-access papers:
LINC01347 is named in the same sentence as 1 disease in open-access papers, as found by Europe PMC text mining. Sharing a sentence is not in itself a finding about the gene and the disease. The quoted sentences say what the papers report.
colorectal cancer (1 paper, 2023). A primary or metastatic malignant neoplasm that affects the colon or rectum. "LINC01347 contributes to the 5-FU chemotherapy resistance of colorectal cancer and suppresses trophoblast cell migration, invasion, and EMT." (PMID 36829596, 2023).